DEFB121 (defensin beta 121)
Description:
Has antibacterial activity.
Synonyms: DEFB-21; DEFB21; ESC42RELC
Tractability: Antibody: UniProt places it where antibodies can reach, with high confidence; UniProt predicts a signal peptide or a membrane-spanning region; its Gene Ontology location is reachable by antibodies, with medium confidence.
Gene: Protein-coding gene on chromosome 20 (31,404,845 to 31,412,838, reverse strand). Ensembl gene ENSG00000204548.
Subcellular location: Secreted
Pathways (Reactome):
Immune System: Beta defensins; Defensins
Gene Ontology:
Molecular function: protein binding; membrane destabilizing activity
Biological process: innate immune response; killing of cells of another organism; defense response to Gram-negative bacterium
Cellular component: extracellular region
Genetic constraint (gnomAD): Loss-of-function variants: 6 observed, 3.13 expected, observed/expected ratio (o/e) 1.92, 90% interval 0.87 to 1.96. That is too few expected variants to judge how well the gene tolerates losing a copy. Missense variants: 87 observed, 88.89 expected, observed/expected ratio (o/e) 0.98, 90% interval 0.82 to 1.17. Synonymous variants: 39 observed, 33.69 expected, observed/expected ratio (o/e) 1.16, 90% interval 0.89 to 1.51.
Homologues: Orthologues: chimpanzee DEFB121 (99% identical), macaque DEFB121 (93% identical), dog DEFB121 (54% identical), pig DEFB121 (53% identical), mouse Defb22 (26% identical), rat Defb22 (21% identical). Paralogues in human: DEFB118 (41% identical), DEFB123 (41% identical), DEFB135 (37% identical), DEFB132 (33% identical), DEFB115 (32% identical), DEFB116 (32% identical), DEFB128 (32% identical), DEFB124 (30% identical), DEFB129 (29% identical), DEFB134 (29% identical), DEFB119 (28% identical), DEFB125 (28% identical), and 7 more.